HK2 (hexokinase 2)
Diseases named in the same sentence as HK2 in open-access papers (continued):
Sharing a sentence is not in itself a finding about the gene and the disease.
tumor (continued). "We observed lower tumor expression levels of GLUT1, HK2, G6pdx and PKM2, and higher expression levels of Atp5b gene in the DEN-treated LIrs1KO mice as compared to the DEN-treated control mice, suggesting that the Warburg effect was suppressed in the tumors from the DEN-treated LIrs1KO mice." (PMID 28710407, 2017). "In summary, the present studies highlight miR-143 as a tumor suppressor in OSCC by the suppression of cell migration, glucose metabolism and proliferation through directly targeting HK2, rendering miR-143 a therapeutic strategy for the treatment of clinical OSCC patients." (PMID 28174335, 2017). "In addition, resveratrol treatment induces late hypermethylation in the promoter region of hexokinase 2 (HK2), an important oncogene involved in maintenance of glycolysis needed to sustain exacerbated cell proliferation and growth of tumor cells." (PMID 27355345, 2016). "Disruption of tumor metabolism through HK2 inhibition must occur early in GBM treatment, and ideally HK2 inhibition would be prolonged and continuous, as this may lead to the greatest survival benefit." (PMID 27588472, 2016). "Although studies have demonstrated an essential role of aerobic glycolysis for cultured cell proliferation and LDHA for tumor xenograft growth, the role of HK2 in mouse tumorigenesis had not been previously established." (PMID 23342984, 2013). "Since VHL-PHEOs/PGLs have a better prognosis than SDHB-PHEOs/PGLs, the difference in HK2 does not seem to contribute to their distinct tumor aggressiveness in these particular tumors." (PMID 22859959, 2012). "HK2 and CKA expression may have biologic and prognostic significance in HCC, with tumor HK2 expression being a potential independent predictor of survival." (PMID 23071593, 2012). "Tumor HK2 expression, but not CKA expression, remained a significant predictor of survival in multivariable analyses." (PMID 23071593, 2012). "Furthermore, H. pylori-induced immune responses and the hypoxic conditions within the tumor niche activate HIF-1α, which collaborates with BRD4 to upregulate glycolysis-related genes such as Slc2a1 (Solute Carrier Family 2 Member 1) and Hk2 (hexokinase 2)." (PMID 41171531, 2026). "The tumor suppressor NDRG2 inhibits metabolic reprogramming through a dual mechanism: it directly reduces PKM2 expression, limiting pyruvate production, while concurrently inhibiting c-Myc transcriptional activity, which in turn suppresses GLUT1- and HK2-mediated glucose uptake and phosphorylation." (PMID 40842995, 2025). "Hypoxic tumor cores exhibit glycolytic dependency mediated by HIF-1α stabilization, targetable through HIF-1α inhibitors (adamantane derivatives, MO-2097, NLG207, NB-5-MT), combined with glycolytic enzyme blockade (HK2 inhibitor PF-04691502, LDHA inhibitor FX-11)." (PMID 40725147, 2025). "Consistent with the in vitro results, tumor growth was impeded by MCL1 depletion and HK2 overexpression partially restored the growth of MCL1-depleted tumors, suggesting a role for modulation of HK2- mediated bioenergetics in the tumor-promoting effects of MCL1." (PMID 41326406, 2025). "Considering that HK2 enables to modulate autophagy and apoptosis resistance through its canonical and noncanonical functions in tumor cells, HK2 may be a prospective candidate target for overcoming MDR." (PMID 40612109, 2025). "However, Hk2 KD did not exert additional tumor suppression activity, suggesting that the immunological effect of glycolysis on tumor growth was mediated by tumor-infiltrated macrophages." (PMID 39883522, 2025). "The glycolytic genes, HK2, GAPDH and ENO1, were chosen as they mediate early, mid and final stages of glycolysis respectively, and all three ketolytic genes BDH1, OXCT1 and ACAT1 were analysed for MYCN amplification, survivability and tumour stage progression in three NB datasets." (PMID 41420301, 2025).
tumor (continued). "This study clarified that HK2, as a glucose receptor, can sense intracellular glucose level and link energy metabolism with tumor immunity through the conversion of classical and non-classical functions, revealing the mechanism of Warburg effect promoting tumor immune escape." (PMID 39897050, 2025). "Notably, simultaneous overexpression of several non-canonical glycolytic isoforms (HK2, HK3, HKDC1, ALDA, GAPDHS, and PGK2), previously linked to tumor development and progression, has been observed in patients with AUD." (PMID 41009047, 2025). "The glycolytic enzyme HK2 has recently been found to perform nonglycolytic activities in cancer, including regulation of transcription, anti-apoptotic, scaffolding activities, and protein kinase activities mediating tumor immune evasion." (PMID 40956859, 2025). "In contrast, the regulation of HK2 by tumor suppressors is usually negative." (PMID 39991762, 2025). "However, tumor cells often overexpress glucose transporter 1 (GLUT1) and hexokinase 2 (HK2), leading to excessive glucose uptake and depletion of extracellular glucose, which limits mTORC1 activation in effector T cells and impairs their proliferation and interferon‐γ (IFN‐γ) production." (PMID 40940612, 2025). "Furthermore, while glycolytic genes (HK2, GAPDH, ENO1) correlate with poor survival, the analysis cannot establish whether their upregulation drives tumour aggression or is a secondary effect of MYCN‐mediated metabolic reprogramming." (PMID 41420301, 2025). "Additionally, the protein levels of GLUT1, LDHA, HK2 and VEGF in tumor tissues declined with melittin treatment compared with the hypoxia group, and the levels of these proteins were remarkably increased in the hypoxia+melittin+si-LATS2 group compared to that in the hypoxia+melittin group." (PMID 38889502, 2024). "Therefore, we speculated that SMAD4 plays a tumor suppressive role by upregulating ARHGAP10 expression and further inhibiting the PI3K/AKT/HK2 pathway." (PMID 38230565, 2024). "Thus, inhibition of HK2 activity using a non-specific inhibitor remodels tumor vasculature and enhances the delivery and efficacy of a chemotherapy drug." (PMID 38798921, 2024). "HK2 can act as a protein kinase and phosphorylate IκBα at T291, leading to NF-κB-dependent upregulation of PD-L1 expression, which suppresses CD8 T cell activation and infiltration into tumor tissues, accelerating brain tumor growth and increasing resistance to immune checkpoint blockade therapy." (PMID 39877360, 2024). "HK2 is present in the outer mitochondrial membrane with voltage-dependent anion channel 1 (VDAC1), where it can access the newly synthesized ATP and regulate the tumor cell glucose metabolism, supporting cell proliferation, migration and resistance to apoptosis." (PMID 38529190, 2024). "In the SHH subtype of MB, the regulation of specific metabolic genes, including hexokinase 2 (Hk2) and fatty acid synthase (FASN), by Hedgehog (Shh) was found to shift the metabolic pattern toward aerobic glycolytic metabolism and lipid synthesis to maintain tumour growth." (PMID 38553479, 2024). "Moreover, the results of Western blotting also demonstrated that knockdown of HK2 could markedly suppress the expression of Bcl-2 and p-ERK and increase the expression of Bax in tumor tissues." (PMID 37854321, 2023). "The combination of HK2 with GSK3 and PKA regulatory subunit RIa could promote GSK3 phosphorylation, thus affecting the epithelial mesenchymal transformation and metastasis of tumor cells." (PMID 37779163, 2023). "This miRNA downregulated expression of glycolytic enzyme Hexokinase 2 (HK2), which gene is frequently overexpressed in malignant tumors by mammalian target of rapamycin activation, decreases glucose metabolism, prevents cancer cell development, and inhibits tumor development over targeting HK2." (PMID 37986065, 2023).
tumor (continued). "However, studies have demonstrated that the knockdown of HK2 alone does not inhibit in vivo tumor progression with reduced glucose consumption, suggesting that HK1 compensates for the overall tumorigenic potential." (PMID 37109475, 2023). "In addition, only HIF-1α expressing neutrophils were significantly increased in proportion in the tumor tissue compared to GLUT1+ and HK2+ neutrophils, highlighting that HIF-1α may have an important role in tumor progression." (PMID 36614196, 2023). "In addition, HIF-1α, HK2, and PKM2 were greatly accumulated in tumor-infiltrating DCs." (PMID 36821379, 2023). "Under the condition of accelerating the growth of tumor cells, the metabolic pathway changes from oxidative phosphorylation to the glycolytic pathway, which is mainly realized by upregulating the glycolysis-related proteins GLUT1, HK2, and PDK1 mediated by HIF-1α." (PMID 35350760, 2022). "Although the proportion of Tregs to total immune cells did not significantly differ according to tumor HK2 expression, the proportion of Tregs to CD4 + T-cells showed a significant positive correlation with tumor HK2 expression (spearman rho = 0.480, P = 0.003)." (PMID 36320008, 2022). "Here, the TCGA database analysis showed that GLUT1, HK2, and other key glycolytic enzymes were highly expressed in and negatively correlated with the survival of HCC patients, suggesting they might be used as a new generation of tumour markers." (PMID 35665592, 2022). "During tumor growth, reprogrammed glucose metabolism is involved to meet the demand of glycolytic intermediates for macromolecule biosynthesis, during which the NSD2 has been reported to play a role by regulating key glucose metabolism regulators, such as TIGAR, HK2, and G6PD." (PMID 35354439, 2022). "Tumor cell lines may exhibit the direct induction of HK2 expression by glucose, whereas non-malignant human cells in primary culture do not." (PMID 35216280, 2022). "We also analyzed the transcriptomics datasets from TCGA primary tumor samples (10,496 cases in total) and GTEX normal tissue samples (7,792 cases in total) from UCSD Xena, and found that the expression level of galectin-3 was correlated with that of HK2 and PKM in all data." (PMID 36481721, 2022). "C-Myc can drive glycolysis; upregulate lactate dehydrogenase A (LDHA), hexokinase 2 (HK2), and pyruvate kinase M2 (PKM2); improve the transcription rate of glucose transporter (GLUT); regulate the transcription of monocarboxylate transporters (MCT); and promote tumor growth." (PMID 34434922, 2021). "Similarly, treatment with LoVo cells with EVs secreted by mouse xenograft tumours‐isolated TANs, but not with those from murine PNs, elevated the expression levels of HK2 and PGK1, while silencing of Spi1 in TANs prevented these changes." (PMID 34841706, 2021). "In line with this, the lactate levels increased both in tumor and peritumoral tissues, as well as the expression of glutamine transporters (i.e., SLC1A5) and glycolytic enzymes, such as glucose-6-phosphate isomerase (GPI), phosphoglycerate kinase (PGK1), aldolase A (ALDOA) and hexokinase 2 (HK2)." (PMID 33924061, 2021). "Metformin can block tumor progression induced by inflammasome activation in tumor-infiltrating immune cells, protect the intestinal barrier from the LPS-triggered damage by alleviating NF-κB phosphorylation, and directly inhibit the enzymatic activity of HK1 and HK2." (PMID 33980323, 2021). "By inducing glycolysis-related genes products such as hexokinase 2 (HK2), lactate dehydrogenase A (LDHA), and glucose transporter 1 (GLUT1, also known as solute carrier family A1, SLC2A1), HIF-1α switches the glucose metabolism of hypoxic tumor cells to the glycolytic pathway." (PMID 35096814, 2021).
tumor (continued). "In addition, to confirm that HK2 can regulate EMT in CRC, we performed IHC staining to detect TJP1, E‐cadherin, vimentin and Twist1 expression in the tumour tissues of CRC patient samples, and the immunohistochemical staining of these proteins exhibited different degrees of positivity." (PMID 34378321, 2021). "Likewise, the correlation between KRAS and glycolysis was further reinforced by immunostaining analysis in CRC tissues, which revealed that tumors with mutant KRAS had a higher expression of tumor glycolytic enzymes, including GLUT1, GLUT3, and HK2, than the tumors with wild-type KRAS." (PMID 33833221, 2021). "Moreover, the results of this study showed that after treatment with andrographolide, the expression levels of the glycolysis-related proteins HK2, PKM2, PFKM, and LDHA in 8505C and CAL62 thyroid cells decreased, further proving that andrographolide can inhibit glycolysis in ATC tumor cells." (PMID 34335811, 2021). "HIF-1α is a master transcriptional factor that controls tumor metabolic reprogramming, given that HIF-1α target genes HK2, Glut1 and MCT4, major enzymes of glycolytic pathway, were elevated in etoposide-treated NSCLC cells, we explored whether etoposide also impacted HIF-1α expression." (PMID 33097055, 2020). "Similarly, HK2 and GAPDH are key mediators of aerobic glycolysis and promote tumor growth." (PMID 32500034, 2020). "With extensive studies, including the present investigation, showing that HK2 is a master promoting factor in different stages of carcinogenesis, much efforts were put in exploring HK-mediated tumor inhibitors, despite that no potent drugs targeting HK2 are yet available in clinic." (PMID 32195170, 2020). "Finally, we showed that the combination of HK2 ablation and metformin treatment, which decreased the compensatory up-regulated oxygen respiration under HK2 depletion, could enhance lung SCC cell death and inhibit tumor cell growth." (PMID 32083006, 2020). "Mechanically, the tumor-suppressive effects of CD36 were mediated through promoting the proteasome-dependent ubiquitination of GPC4, and the degraded GPC4 failed to activate β-catenin/c-myc signaling cascades and downstream glycolytic target genes GLUT1, HK2, PKM2 and LDHA." (PMID 31484922, 2019). "Indeed, inhibitors of glycolytic enzymes such as hexokinase 2 (HK2), phosphofructokinase 2 (PFK2), pyruvate kinase M2 (PKM2), lactate dehydrogenase A (LDHA), and pyruvate dehydrogenase kinase (PDK) show anti-tumor effects." (PMID 30602670, 2018). "To determine whether the CT inhibited the expression of STAT3, SIRT3, HIF‐1α, GLUT1, LDHA, and HK2 in vivo, we performed qRT‐PCR to detect these genes expression in tumor tissues from the mouse with or without the treatment of CT." (PMID 30094960, 2018). "The combination of shRNA HK2 knockdown and daily DPI i.p. injection at 2 mg/kg did not cause HK1−HK2+ liver tumor cell apoptosis, suggesting that DPI at this dosage, in combination with HK2 knockdown, is not sufficient to cause lethality of HK1−HK2+ tumor cells in vivo." (PMID 29988332, 2018). "It is possible that presence of HK2 may sensitize DLBCL patients to currently used CHOP-based treatment by depriving dependence of tumors on glucose consumption for its growth and interfering with metabolic needs of tumor." (PMID 29335581, 2018). "Conversely, increased expression of the glycolysis gatekeeper hexokinase 2 in tumor cells facilitated tumor escape from CD4+ T cell-mediated immune surveillance, further corroborating the importance of metabolic competition between tumor-infiltrating lymphocytes (TILs) and tumor cells." (PMID 30131808, 2018). "However, it has been identified that miR143 suppresses tumor cell growth and migration, silencing the KRAS (V-Ki-ras2 Kirsten rat sarcoma viral oncogene homolog) gene, and adjusting glucose metabolism via the miR143/HK2 axis." (PMID 29258429, 2017).
tumor (continued). "The following effects were observed with HK2 knockdown: inhibition of cell migration and invasion; reduced SOD2 activity and intracellular H2O2 levels; suppression of pERK1/2, Slug and Vimentin expression; and inhibition of tumour growth and lung metastasis in vivo." (PMID 27926482, 2017). "Using cell lines and primary cultures of GBM, we showed that inducible knockdown of HK2 altered tumor metabolism, which could not be recapitulated by HK1 or HK3 loss." (PMID 27588472, 2016). "Furthermore, the DU145 hK2-negative xenografts showed significantly lower (P = 0.01) tumour accumulation for 111In-DTPA-11B6, 4.8 ± 0.86%IA/g compared to 17 ± 5.2%IA/g at 48 h." (PMID 26116115, 2014). "Higher concentrations of PSA and hK2 were found in tumours expressing steroid hormone receptors (P = 0.0001 for PSA and P = 0.0001 for hK2, by Wilcoxon tests for both ER and PR), and both PSA (r = 0.25, P = 0.0001) and hK2 (r = 0.22, P = 0.0001) correlated directly with PR levels." (PMID 10646889, 2000). "We showed that RD and HFD create different metabolic environments in the breast microenvironment (e.g., increased glycolysis (HK2) and p-AMPK in RD-fed mice compared to HFD-fed mice), which may differently influence energy metabolism in the TME during tumorigenesis and replication of tumor cells." (PMID 36675341, 2023). "The results suggested that, the high expression of C1orf74, HK2, SLC22A3, SNX10 and URB2 and Neutrophils, as well as the low expression of RASSF5 and CD8+ T cells was related to the poor prognosis of CC patients, which might serve as the key prognostic biomarkers of tumor." (PMID 36354693, 2022). "Consistently, knockdown of HK2 in Tca8113 cells significantly suppressed cells proliferation, invasion and glucose metabolism compared with control siRNA transfection, indicating deregulation of HK2 by miR-143 might be a therapeutic approach for OSCC tumor treatments." (PMID 28174335, 2017). "Our results show highly elevated expression levels of HK2 and HIF1A in PHCs and HCC-PHHs in comparison to non-HCC-PHHs, indicating a hypoxic (peri-)tumor environment." (PMID 36077764, 2022). "The HK1 and HK2 proteins are both highly expressed in KRAS-mutant mouse lung tumors, while the activation of HK2 but not HK1 is inevitable for tumor initiation and progression." (PMID 36532721, 2022). "In contrast, the PSA-, hK2-, and FAP-based TG prodrugs at their ten-fold lower MTD (i.e., ~4 μmoles/kg/dose) stop tumor growth, but do not produce tumor regression." (PMID 34946547, 2021). "In this study, we found that HK2 is highly expressed in lung SCC, but not in lung ADC, and is required for tumor growth." (PMID 32083006, 2020). "In this study we build on our prior work to show that HK2, but not the other brain-specific isoforms of hexokinase, HK1 and HK3, drives tumor metabolism in GBM." (PMID 27588472, 2016). "The decrease in FDG uptake was paralleled by decreases in GLUT1 and HK1 expression, whereas no change in HK2 expression was observed suggesting that GLUT1 and HK1 are involved in the FDG uptake in this tumor model." (PMID 24386456, 2013). "Non-mitochondrial HK2 directly interacted with CD133, which inhibited CD133 polyubiquitylation and degradation, thereby promoting small cell lung cancer cell proliferation and tumor growth." (PMID 40880642, 2025). "Herein, function of FGFRi's tumor inhibition may not be actioned simply by FGFR pathway; FGFR inhibition induced HK2 reduction via AKT-mTOR signaling to regulate glucose metabolism was indicated in the FGFRi-sensitive cells." (PMID 36168616, 2022). "We conclude (i) that inhibition of HK2-driven glycolysis, OXPHOS, and FAO is likely to be a pan-tumor precision therapy approach to HK1−HK2+ tumors, regardless of their tissue of origin, and (ii) that cancer therapies that involve HK2 inhibition will be restricted to tumors that do not express HK1." (PMID 29988332, 2018).
tumor (continued). "Although analysis of cell lines from the CCLE collection revealed that most HCC cell lines express only HK2 and not HK143,44, we found that HCC cells hijacked lEV HK1 secreted from activated HSCs to enhance their proliferation, reflecting the resourcefulness of tumor cells." (PMID 36192599, 2022).